GCG (glucagon)
Diseases named in the same sentence as GCG in open-access papers (continued):
Sharing a sentence is not in itself a finding about the gene and the disease.
diabetes (continued). "In our study there was a non-significant lower fasting glucagon levels after the Palaeolithic diet compared to the diabetes diet, which could be a result of the amelioration of leptin sensitivity in the pancreatic islets." (PMID 27216013, 2016). "Using these two strategies they were able to elegantly show that if virtually all the β-cells were destroyed, blocking the glucagon signal could not prevent diabetes." (PMID 27190125, 2016). "The fact that diabetic patients have too little insulin, as well as uncontrolled levels of glucagon, has led to the hypothesis that diabetes is triggered by inappropriate levels of both hormones, not just insulin alone." (PMID 27190125, 2016). "However, several researchers have recently reported that mice lacking the receptor for glucagon do not develop diabetes when their β-cells are destroyed." (PMID 27190125, 2016). "However, cells that co-express insulin and glucagon were never found in our samples from controls or diabetics." (PMID 26057531, 2015). "In the present study, we showed that mice deficient in proglucagon-derived peptides are resistant to diet-induced obesity but develop diabetes mellitus due to defective β-cell compensation, indicating that glucagon is not a prerequisite for development of diet-induced diabetes." (PMID 26378455, 2015). "One could speculate that some knock-outs procedures may alter the physiology of insulin-glucagon interactions, and may reflect a metabolic system not seen in physiology or in diabetes." (PMID 22969729, 2012). "Our results further suggest that completely inhibiting glucagon signaling may not be a safe approach to treat diabetes." (PMID 21853126, 2011). "Our results suggest that complete inhibition of glucagon signaling may not be a safe approach to treat diabetes." (PMID 21853126, 2011). "In several studies in subjects with diabetes, GLP-1- whether administered by intravenous or subcutaneous infusion – normalized both fasting and postprandial glycemia by enhancing glucose-mediated insulin secretion, as well as by suppressing glucagon secretion." (PMID 19619327, 2009). "However, we did not demonstrate elevated glucagon levels relative to participants without diabetes." (PMID 41285865, 2025). "A more recent study evaluated the effects of 35 g of fermented and non-fermented chokeberry in type 2 diabetes mellitus patients, and no statistically significant influence was recorded in terms of waist circumference, insulin sensitivity or fasting levels of glucose, insulin or glucagon." (PMID 39330724, 2024). "We could not investigate the glycaemic threshold for the glucagon response in people with diabetes." (PMID 35867127, 2022). "Similarly, units of glucagon per person with diabetes were not different between the two Groups." (PMID 36550552, 2022). "There is therefore reasonable quality data from more than one independent study to suggest that diabetes mellitus, pancreatitis, chronic kidney disease and cirrhosis may be potential reasons for elevated circulating glucagon levels in the absence of a glucagonoma." (PMID 33391185, 2020). "Therefore, inhibiting glucagon secretion, rather than blocking the glucagon receptor, may be a more appropriate therapeutic approach for the treatment of hyperglucagonemia of diabetes." (PMID 32117057, 2020). "However, as previously discussed, Xen infusions and/or oral bethanechol also increased postprandial cholinergic signaling in humans with normal glucose tolerance, impaired glucose tolerance, and type 2 diabetes mellitus without affecting ISRs or glucagon levels." (PMID 29466430, 2018). "Therefore, a preferable strategy may be to control the secretion, rather than the action, of glucagon for improved glycemic control in diabetes." (PMID 30713523, 2018). "Moreover, an increase of α-cells or glucagon-secreting cells in damaged islets might be a negative factor in diabetes." (PMID 29073149, 2017).
diabetes (continued). "However, when the majority, but not all, of the β-cells are destroyed, blocking the glucagon signal could prevent the mice from developing diabetes." (PMID 27190125, 2016). "The lack of glucagon increase after melatonin treatment in GK rats may be a consequence of impaired insulin secretion or disturbed α-cell sensitivity for glucose, as is characteristic in diabetes." (PMID 23535335, 2013). "Suppression of glucagon action on target organs may be a secondary mechanism underlying the antihyperglycemic efficacy of GLP-1 analogs and DPP-4 inhibitors, but there are no approved treatments for diabetes that directly target glucagon secretion or glucagon action in target organs." (PMID 23185367, 2012). "In addition, the incidence of diabetes is enhanced in transgenic IL-10-NOD mice expressing IL-10 in the glucagon-producing α-cells of the pancreas, and adoptive transfers of prediabetic or diabetic wild-type NOD splenocytes into these transgenic IL-10-NOD mice accelerates diabetes." (PMID 21716731, 2011). "In patients with type 1 diabetes mellitus in the DK/DKA group, the plasma glucagon level was negatively correlated with serum CPR and serum CPR/plasma glucose ratio, suggesting relationships with decreased insulin secretion and hyperglucagonemia." (PMID 41292690, 2026). "A glucagon and GLP-1 receptor dual agonist which has had recent phase two completion, including adults between 18–75 years, BMI ≥ 27 kg/m2, without diabetes." (PMID 38710803, 2025). "We performed insulin/glucagon/vimentin and SRFG staining in sections from ten organ donors without CF, diabetes or established chronic pancreatitis." (PMID 39836539, 2025). "In overweight individuals without diabetes, dual GLP-1/glucagon infusion increased the energy expenditure to a similar degree as glucagon alone; however, the addition of GLP-1 reduced the hyperglycemic effect of glucagon." (PMID 36767008, 2023). "In this perspective, the ideal IDE inhibitor to treat diabetes should inhibit the clearance of insulin and amylin without affecting the catabolism of other IDE substrates, such as glucagon or amyloid beta peptides." (PMID 37892174, 2023). "Immunostaining of human pancreata revealed an increased number of CADM1+glucagon+ cells adjacent to CD8+ T cells in sections from T1D and aAb+ donors compared with individuals without diabetes." (PMID 35133983, 2022). "In this clinical study, we found that empagliflozin decreased insulin, increased glucagon, and increased NEFAs and BHB blood levels in individuals without diabetes." (PMID 36359767, 2022). "GCG, IRS1, VEGFA, STAT3, CCL2, CASP3, and APOE are the 7 DEPs that are related to diabetes mellitus as specific proteins but not seen among the central proteins of fatty liver disease." (PMID 35154608, 2021). "Thus, we determined incretin levels in addition to glucagon level using the bioassays in type 2 diabetes mellitus (T2DM) subjects with or without treatment of DPP-4 inhibitor, to evaluate whether these assays can accurately measure bioactivity of these peptides." (PMID 32390941, 2020). "Therefore, the role of pancreatic α-cells and glucagon secretion has been revisited and type 2 diabetes mellitus (T2DM) is considered as a bi-hormonal defect proposing that diabetic hyperglycaemia would not develop unless the lack of insulin was accompanied by hypersecretion of glucagon." (PMID 32218947, 2020). "This is an insulinopenic model of diabetes with degraded pancreatic islet cells by radicals produced by STZ, and plasma glucagon level did not change significantly with BFM treatment." (PMID 29318388, 2018). "Although pancreatic islets are center stage in diabetes, the impact of RYGB on islet function, especially on glucagon secretion, has not been fully elucidated." (PMID 27117413, 2016).
diabetes (continued). "The patient was suspected of having type 2 diabetes mellitus because all islet-related antibodies were negative and delta C-peptide (CPR) level after glucagon loading (6 min after glucagon loading - before glucagon loading) was 1.1 ng/mL." (PMID 21492449, 2011). "Additionally, PDCD1 did not correlate with time since diabetes diagnosis, INS, or GCG, suggesting a lack of a direct link between islet hormone depletion and PD-1–mediated immune modulation." (PMID 40244011, 2025). "The overall results suggest that maternal RUPP has negative and sex-specific impacts on insulin, glucagon and ghrelin regulations in offspring and that, as young adults, male RUPP rats may be more prone to develop obesity and diabetes." (PMID 36109770, 2022). "In overweight individuals without diabetes, dual GLP‐1/glucagon infusion increased energy expenditure to a similar degree as glucagon alone; however, the addition of GLP‐1 reduced the hyperglycemic effect of glucagon." (PMID 34713962, 2022). "Twenty patients of active acromegaly (10 each, with and without diabetes) underwent hyperinsulinemic euglycaemic clamp and mixed meal test, before and after surgery, to measure indices of IS, β-cell function, GIP, GLP-1 and glucagon response." (PMID 30948746, 2019). "After this time point Ngn3 was not detectable in control mice; however, in diabetic NOD mouse islets undergoing remodeling we found Ngn3-expressing cells usually colocalized with glucagon, whereas no Ngn3-positive cells were detected in the islets of Balb/c mice with STZ-induced diabetes." (PMID 25101835, 2014). "By contrast, levels of circulating glucagon remained constant in NOD mice as the disease progressed, in accordance with our finding that alpha-cell mass does not increase as beta-cells are lost in this mouse model of diabetes." (PMID 25101835, 2014). "Interestingly, icv leptin administration also normalizes excessive glucagon secretion and HPA axis activity in uncontrolled diabetes, whereas icv FGF1 injection does not — and yet, both appear to inhibit AgRP neurons, activate POMC neurons, and thereby increase net melanocortin signaling." (PMID 40371641, 2025). "The AAV GCG-EGFP allows for the identification of mouse α-cells without the need to cross in a reporter strain, consequently reducing the number of mice that are generated and also allowing for the study of α-cells from different strains, such as various diabetes-prone mouse strains." (PMID 31346189, 2019).
type 2 diabetes (1,014 papers, 2008 to 2026). "GLP-1 RAs improve glycaemic control through glucose-dependent insulin secretion, glucagon suppression, slowed gastric emptying, and enhanced satiety, yielding HbA1c reductions, weight loss, and cardiovascular benefits in type 2 diabetes." (PMID 41226286, 2025). "In contrast to type 2 diabetes, the pathophysiology is dominated by combined endocrine failure (e.g., deficient β-cell insulin and α-cell glucagon secretion) together with malabsorption from exocrine insufficiency and systemic inflammation." (PMID 41226286, 2025). "Type 2 diabetes is associated with hypersecretion of somatostatin, which has implications for paracrine regulation of insulin and glucagon secretion." (PMID 39803760, 2025). "Increased plasma levels of glucagon (hyperglucagonaemia) are associated with fasting hyperglycaemia in people with type 2 diabetes but are also observed in individuals with obesity and/or MASLD." (PMID 38705923, 2024). "Elevated levels of endogenous glucagon (hyperglucagonaemia) have been linked with hyperglycaemia in individuals with type 2 diabetes but are also observed in individuals with obesity and MASLD." (PMID 38705923, 2024). "Type 2 diabetes development is associated with elevated glucagon levels—both due to chronic hypersecretion but also to impaired suppression by hyperglycemia—and downregulated GH levels." (PMID 37708362, 2024). "As well as direct effects of excess lipid potentially impairing hepatocyte sensitivity to glucagon, there are several additional potential causes for fasting and post-prandial hyperglucagonaemia in people with type 2 diabetes." (PMID 38579751, 2024). "Increased fecal propionate has been associated with increased risk of type 2 diabetes, and supplementation with propionate has been found to increase plasma levels of glucagon and insulin, increasing the risk of insulin resistance and weight gain." (PMID 38262952, 2024). "The fasting glucagon to insulin ratio is inversely associated with metabolic syndrome in patients with type 2 diabetes." (PMID 37762748, 2023). "Clinical cross-sectional study of patients with Type 2 diabetes mellitus indicated that lower fasting and postprandial glucagon-to-insulin ratio was significantly associated with the presence of NAFLD." (PMID 36942499, 2023). "The subjects were originally recruited based on their genotype at rs7903146 in the TCF7L2 locus where the T (the type 2 diabetes‐associated) allele increased disorderliness of insulin secretion and impaired postprandial suppression of glucagon." (PMID 35822422, 2022). "Another strong regulator of plasma glucagon is insulin, and insulin resistance and type-2-diabetes are strongly associated with both fasting and postprandial hyperglucagonemia." (PMID 36088386, 2022). "Disrupted expression of TLE1 was observed in human type 2 diabetes and is associated with an increased proportion of glucagon-expressing cells." (PMID 36620623, 2022). "Characteristics of the secretion of the pancreatic and intestinal products are described, and causes of the hypersecretion of glucagon in obesity and type 2 diabetes are discussed." (PMID 35990325, 2022). "In conclusion, we reproduced the suggested association between liver fat, the glucagon–alanine index and insulin resistance in an independent study cohort of young women with low to high risk for type 2 diabetes." (PMID 33275161, 2021). "ATP surplus in the pancreatic β-cells and α-cells causes excess secretion of insulin and glucagon, respectively, leading to peripheral insulin resistance in the early phase of type 2 diabetes." (PMID 34987473, 2021). "A type 2 diabetes risk variant in the EYA2 locus was associated with higher plasma glucagon levels at 30 min." (PMID 33407418, 2021).
type 2 diabetes (continued). "As we will discuss later, this further justified the development of synthetic GLP-1/glucagon co-agonists as promising weight loss therapeutics, particularly in the context of avoiding unwanted hyperglycaemia in obesity-associated type 2 diabetes." (PMID 34566894, 2021). "A known type 2 diabetes variant in EYA2 was significantly associated with higher plasma glucagon level at 30 min during the OGTT (Beta 0.145, SE 0.038, P = 1.2 × 10–4) corresponding to a 7.4% increase in plasma glucagon level per effect allele." (PMID 33407418, 2021). "Our results are in line with two other studies that showed decreased fasting and postprandial glucagon levels after a mean weight loss of 10 kg in individuals with type 2 diabetes." (PMID 34382579, 2021). "An insufficient release of insulin combined with impaired regulation of glucagon secretion is a hallmark of type-2 diabetes." (PMID 33810265, 2021). "We reproduced the previously reported association of liver fat content and HOMA-IR with the glucagon–alanine index in an independent study cohort of young women with low to high risk for type 2 diabetes." (PMID 33275161, 2021). "In order to explore the pathophysiology underlying type 2 diabetes we examined the impact of gene variants associated with type 2 diabetes on circulating levels of glucagon during an oral glucose tolerance test (OGTT)." (PMID 33407418, 2021). "We only identified one of the current known type 2 diabetes risk alleles to associate with glucagon levels during OGTT." (PMID 33407418, 2021). "There is also evidence that the glucagon response is lost in advanced type 2 diabetes with severe endogenous insulin deficiency." (PMID 34405569, 2021). "TCF7L2 SNPs are strongly associated with various aspects of type 2 diabetes, including insulin resistance, impaired insulin secretion, altered insulin processing, diminished suppression of glucagon by glucose, and increased fasting hepatic glucose release." (PMID 33828529, 2021). "In patients with type 2 diabetes (T2D), pancreatic fat associated with a reduction of glucagon-stimulated insulin secretion." (PMID 32725157, 2020). "In accord, a recent study demonstrated that several measures of glycemic variability assessed by continuous glucose monitoring were significantly linked to glucagon-stimulated insulin secretion in Japanese patients with type 2 diabetes." (PMID 32775460, 2020). "These inquiries are particularly important in the context of the pathophysiology of type 2 diabetes, in which hyperinsulinemia, an imbalance in insulin/glucagon levels, and insulin resistance are associated with the development and progression of the disease." (PMID 32698380, 2020). "Dysregulated glucagon drives hyperfunction in hepatic glucose output, which is the main cause of persistent hyperglycemia in type 2 diabetes." (PMID 31976031, 2020). "High glucagon secretion is an important risk factor for impaired glucose tolerance and type 2 diabetes." (PMID 29242971, 2019). "In particular the stimulation of beta cell function and inhibition of glucagon secretion were important, since insufficient insulin secretion and hypersecretion of glucagon were at that time emerging as the key defects underlying type 2 diabetes." (PMID 31275243, 2019). "In this study, we explored glucagon suppression and its relationship with insulin resistance in subjects on atorvastatin therapy at high risk for type 2 diabetes." (PMID 31546230, 2019). "Type 2 diabetes is associated with dysregulated glucagon secretion, and increased glucagon concentrations contribute to the diabetic hyperglycemia." (PMID 31068828, 2019). "In the present study, we examined plasma glucagon concentrations and glucagon suppression after oral glucose intake in a group of individuals at high risk for type 2 diabetes (prediabetes) undergoing atorvastatin therapy." (PMID 31546230, 2019).